KIAA1549 (KIAA1549)
Diseases named in the same sentence as KIAA1549 in open-access papers (continued):
Sharing a sentence is not in itself a finding about the gene and the disease.
melanoma (4 papers, 2013 to 2025). A malignant, usually aggressive tumor composed of atypical, neoplastic melanocytes. "The variant from chromosome 7 next most significantly associated with melanoma in the LLFS data is the minor allele (T) of the rs55750236 SNP located in the KIAA1549 gene." (PMID 23641255, 2013). "The KIAA1549 gene is known for its fusion with BRAF gene involved in the MAPK/ERKs signaling pathway which is thought to play a pivotal role in melanoma as well as other cancer development." (PMID 23641255, 2013). "Several of these fusions, such as the mentioned AGK::BRAF, KIAA1549::BRAF, and MKRN1::BRAF, have been previously reported in melanoma and other solid tumors." (PMID 40737104, 2025). "Additionally, we identified targetable fusions, such as KIAA1549::BRAF, which represent therapeutic opportunities for advanced melanoma, including novel type II RAF inhibitors with potent activity against kinase fusions." (PMID 40737104, 2025).
sarcoma (4 papers, 2014 to 2024). A usually aggressive malignant neoplasm of the soft tissue or bone. "Spindle cell sarcoma with KIAA1549-BRAF fusion is a type of childhood sarcoma that closely resembles infantile fibrosarcoma by morphologic criteria and harbors molecular alteration other than the ETV6-NTRK3 fusion gene." (PMID 38344591, 2024). "Since the KIAA1549-BRAF fusion is also found in adult cancers such as breast cancer and sarcomas, our findings could inform emergent drug resistance in multiple cancers harboring BRAF-fusions." (PMID 29156677, 2017). "Furthermore, specific BRAF-fusions are common across multiple adult and pediatric cancers, including KIAA1549-BRAF found in pediatric gliomas, breast carcinoma, and sarcomas, and MKRN1-BRAF in PLGGS, colorectal carcinoma, and head and neck carcinoma." (PMID 29156677, 2017).
cerebellar pilocytic astrocytoma (3 papers, 2013 to 2022). A WHO Grade 1 astrocytoma which arises in the cerebellum. "The KIAA1549-BRAF fusion is estimated in nearly 80% of cerebellar pilocytic astrocytomas, but only around 50% of non-cerebellar pilocytic astrocytomas, including those of the spinal cord." (PMID 36147920, 2022).
cerebellar tumors (2 papers, 2019 to 2022). "A tandem duplication at 7q34 resulting in a fusion gene between BRAF and KIAA1549 is the most common genetic alteration occurring in 60–70% of pediatric PAs, mainly in tumors of the cerebellum, brainstem and optic pathway; however, its reliable detection is technically challenging." (PMID 31362435, 2019).
leukemia (1 paper, 2020). A malignant (clonal) hematologic disorder, involving hematopoietic stem cells and characterized by the presence of primitive or atypical myeloid or lymphoid cells in the bone marrow and the blood. "In addition, there were no studies of CANT1, KIAA1549, and NFIB on leukemia in previous literatures; therefore, the association between these genes and leukemia should be further investigated." (PMID 32638549, 2020).
spinal cord tumors (1 paper, 2020). "To identify potential new therapy options in pediatric low-grade spinal cord tumors, we evaluated whether these tumors identified at 2 institutions (Children’s Hospital Colorado [CHCO] and SickKids) harbor targetable lesions such as the KIAA1549–BRAF fusion and BRAFV600E mutations." (PMID 33063010, 2020).
spindle cell neoplasm (1 paper, 2014). A benign or malignant neoplasm characterized by the presence of neoplastic spindle cells. "The patient responded to combination targeted therapy that fortuitously targeted KIAA1549-BRAF and PTEN loss within a spindle cell neoplasm, as revealed by genomic profiling based on NGS." (PMID 24422672, 2014).
spindle cell sarcoma (1 paper, 2024). A malignant mesenchymal neoplasm composed of spindle-shaped cells. "Here we present the case of a three-year-old girl who was diagnosed with spindle cell sarcoma with KIAA1549-BRAF fusion gene and had a favorable outcome three years after surgery." (PMID 38344591, 2024).
tumor (59 papers, 2009 to 2025). "The tumour is usually driven by a single oncogenic variant in the MAP Kinase pathway (most frequently a KIAA1549::BRAF gene fusion)." (PMID 39294363, 2024). "In two patient tumor biosamples, we identified diagnostic KIAA1549-BRAF fusion oncogenes, and we also found 16 new SIA-associated fusion transcripts." (PMID 35387112, 2022). "This adds to the complexity of the formation of the KIAA1549-BRAF fusion within this tumour which also has 1 copy loss of the 7q arm where the KIAA1549 and BRAF genes reside." (PMID 34493325, 2021). "• This case is the first report any tumor expressing KIAA1549-BRAF fusion with PTEN loss to be successfully treated by targeted therapy." (PMID 24422672, 2014). "In this paper, we describe a novel KIAA1549:BRAF fusion transcript in a sporadic PA tumor associated with increased ERK activation and review the spectrum of BRAF genetic alterations in this common pediatric low-grade central nervous system neoplasm." (PMID 22548077, 2012). "One tumour possessed a KIAA1549::BRAF fusion alongside VEGFR2, MSH6, and LRP1B variants." (PMID 39948623, 2025). "Another tumour demonstrated partial KIAA1549 inversion in addition to CDK4 and KDM6B variants." (PMID 39948623, 2025). "However, these inhibitors cause paradoxical activation of MAPK pathways by mediating RAF‐independent activation of MEK and ERK when used against tumours that are BRAF wild‐type or KIAA1549‐BRAF fused and can cause increased tumour progression and growth." (PMID 38299304, 2024). "A Clinical Laboratory Improvement Amendments (CLIA) laboratory performed NGS-based diagnostic genomic profiling which identified this tumor as the first reported case of the KIAA1549-BRAF fusion in a PTEN null background as a driving genomic alteration susceptible to targeted therapy." (PMID 24422672, 2014). "The identification of KIAA1549-BRAF fusion in the tumor specimen was achieved using ACTOnco+®, a comprehensive genomic profiling assay." (PMID 40796116, 2025). "The availability of tumor gDNA for a majority of KIAA1549::BRAF fusion cases in our cohort allowed us to verify a concordance between BRAF CNV values and the number of copies of fusion ctDNA." (PMID 38371226, 2024). "The prognostic significance of BRAF V600E mutation and KIAA1549-BRAF fusion appears to be dependent on the histological type of the primary brain tumor, the age of diagnosis, and the tumor location." (PMID 37124503, 2023). "For example, there is some suggestion from their predominantly clonal presence in tumour samples that gain‐of‐function SVs, including certain recurrent oncogenic fusions such as TMPRSS2‐ESG and BRAF‐KIAA1549, occur early in tumour development." (PMID 35355264, 2022). "Conversely, Colin and colleagues argued that the prognostic factors, including patients’ ages, extent of tumour resections and tumour locations of the BRAF-KIAA1549 fusions, are significantly associated with the clinical outcomes." (PMID 33557011, 2021). "To this end, we generated RNA-Seq data (polyA-enriched, TruSeq Stranded, 2 × 100 bp paired-end reads) from 22 fresh-frozen pediatric PA tumor samples, in which a KIAA1549:BRAF fusion had previously been identified by whole-genome sequencing (WGS)." (PMID 32476062, 2020). "Our result showed that the ratio of cells harboring the KIAA1549-BRAF fusion gene in cellular components of MVP to tumor cells was different from S1 (42%) to S6 (76%)." (PMID 31329636, 2019). "The results showed that the ratio of cells harboring the KIAA1549-BRAF fusion was 42% in cellular components of MVP compared to tumor cells in S1 and 76% in S6." (PMID 31329636, 2019). "In both samples, PCR yielded bands for the KIAA1549-BRAF fusion gene in tumor cells and cellular components of MVP." (PMID 31329636, 2019). "In two patient samples with abundant MVP, RT-PCR assay detected strong bands arising from the KIAA1549-BRAF fusion gene in both tumor cells and cellular components of MVP." (PMID 31329636, 2019).
tumor (continued). "Similar effect of trametinib and everolimus co-treatment was observed in vivo with near total inhibition of KIAA1549-BRAF or FAM131B-BRAF driven tumor growth." (PMID 29156677, 2017). "DKFZ-BT66 cells were derived from a primary PA tumor exhibiting the typical and specific KIAA1549:BRAF-fusion (KEX16BEX9)." (PMID 28002790, 2017). "In summary, DKFZ-BT66 displayed a methylation profile similar to primary infratentorial PAs as well as to the primary tumor of origin, expressed and maintained the prototypical KIAA1549:BRAF fusion, and showed the expected MAPK activity." (PMID 28002790, 2017). "This is the first report of a tumor driven by a KIAA1549-BRAF fusion responding to sorafenib-based combination therapy." (PMID 24422672, 2014). "As both tumour types frequently carry KIAA1549::BRAF fusions, identification of the genetic driver may be insufficient to distinguish the tumour types." (PMID 39294363, 2024). "Gene tumor analysis revealed the presence of the KIAA1549-BRAF gene fusion." (PMID 38034149, 2023). "The RET A919P variant along with the inclusion of a downstream pathway member such as the KIAA1549-BRAF fusion (identified in this tumour) may have an amplificative effect on the MAPK pathway." (PMID 34493325, 2021). "This tumour also contained a KIAA1549-BRAF fusion with an unknown highly repetitive DNA fragment inserted within the duplication." (PMID 34493325, 2021). "To determine whether cellular components of MVP and tumor cells in PA harbored the same KIAA1549-BRAF fusion gene, we evaluated cells collected from FFPE slides by laser microdissection." (PMID 31329636, 2019). "Additionally, to further analyze the ratio of cells harboring the KIAA1549-BRAF fusion gene in cellular components of MVP compared to tumor cells, digital PCR with customized primers and Taqman probes was carried out." (PMID 31329636, 2019). "For example, KIAA1549‐BRAF fusions are more common in posterior fossa tumours (up to 90%), compared to supratentorial tumours (33–59%), and BRAF V600E mutations are more frequent in supratentorial tumours (~ 18%) than those in the posterior fossa (~ 3%)." (PMID 28388012, 2018). "KIAA1549:BRAF fusions were analyzed in the LGG cohort and we found the gene fusion slightly more frequent in infratentorial (38.5%) versus supratentorial (25%) tumours, while we didn’t note any difference for BRAF V600E mutation." (PMID 23947815, 2013). "For example, KIAA1549-BRAF has innate resistence to first-generation BRAFi vemurafenib as well as paradoxically triggered by PLX4720 treatment resulting in faster growth of tumor, while it shows a strong response to clinically available MEKi (e.g., trametinib)." (PMID 37397394, 2023). "Collectively, these data suggest a complex and distinct immune phenotype between KIAA1549‐BRAF fusion and BRAF V600E, suggesting the involvement of potentially different immune pathways in these tumor subtypes." (PMID 40588233, 2025). "This alteration results in the formation of the BRAF-KIAA1549 fusion protein (f-BRAF), leading to constitutive activation of the MAPK pathway, which drives tumor growth." (PMID 41050069, 2025). "For example, KIAA1549–BRAF fusions in pilocytic astrocytoma and EWRS1–FLI1 fusions in Ewing sarcoma are prime determinants of these tumor types." (PMID 37400763, 2023). "Subsequent clinical studies examining the use of a type I RAF inhibitors, such as sorafenib, in KIAA1549-BRAF–fused PAs were unfortunately met with paradoxical upregulation of the MAPK pathway and marked tumor growth." (PMID 37124503, 2023). "The majority of rearrangements were KIAA1549-BRAF rearrangements (n = 47; 85%), with only one tumor each harboring BCAS1, CCDC6, GIT2, or PTPRZ11 as a fusion partner." (PMID 36854806, 2023). "We re-analysed this tumor by using an ARCHER® FusionPlex NGS panel and were able to validate a fusion of KIAA1549 exon 14 to BRAF exon 8 in this case." (PMID 35361262, 2022).
tumor (continued). "Some recurrent fusions appear to be almost exclusively clonal (CCDC6-RET, BRAF-KIAA1549, and TMPRSS2-ERG), suggesting that gain-of-function SVs occur early during tumor development." (PMID 33831375, 2021). "For example, a pLGG with typically benign histology, a KIAA1549-BRAF fusion, and arising in a child between 3-12 years would typically be viewed as low risk and a "watch and wait" strategy may be employed, followed by less aggressive therapies if the tumor were to progress." (PMID 32164789, 2020). "The KIAA1549-BRAF fusion gene, resulting from duplication of the BRAF gene at 7q34, is used as a marker of tumor derived cells and phenotypically distinct tumor cells expressing vascular markers; it is the most frequent genetic alteration in PA (>70%)." (PMID 31329636, 2019). "KIAA1549-BRAF fusion events were exclusive to low grade thalamic glioma and were found in 39 % of tested tumours." (PMID 27577993, 2016). "Initial tumor samples were sent for further molecular studies for the purpose of testing the presence of a KIAA1549-BRAF fusion, as it was not tested at first due to the initial unavailability of the test." (PMID 38846974, 2024). "In a KIAA1549::BRAF fusion-driven neural stem cells (NSC) model, CCL2 secreted by the tumor cells, and under the control of the MAPK pathway, was necessary for the recruitment of microglia cells promoting tumor formation." (PMID 38789691, 2024). "Importantly, despite the initial reported specificity in the traditional KIAA1549-BRAF rearrangement for PA, these fusions have subsequently been found to occur in a variety of other tumor histologies." (PMID 37124503, 2023). "Other alterations in addition to the BRAF-KIAA1549 fusion, such as CDKN2A deletions, and tumor location may alter the outcome of the patient." (PMID 37397394, 2023). "Although sufficient quality RNA and tumor-normal paired WGS can be difficult to obtain for certain types of cancer, we could confidently detect lowly expressed gene fusions such as KIAA1549–BRAF and fusions in samples with low tumor cell percentages (30–40%)." (PMID 37400763, 2023). "The retained KIAA1549-BRAF fusion was identified by three callers but was initially filtered out due to too few reads of evidence, possibly due to either low expression, low tumor cellularity or clonality." (PMID 34863095, 2021). "The presence of KIAA1549-BRAF can aid in tumor diagnosis as it is not found in adult-type diffuse glioma and, with rare exceptions, confirms a pLGG diagnosis." (PMID 32164789, 2020). "In the current study we used the KIAA1549-BRAF fusion gene as a marker to assess whether MVPs in PA contained tumor-derived cells and/or phenotypically distinct tumor cells expressing vascular markers." (PMID 31329636, 2019). "We have previously demonstrated that the most common BRAF-fusion in PLGGs, KIAA1549-BRAF, has innate resistance to first-generation RAFi vemurafenib (research analog PLX4720), and instead is paradoxically activated upon PLX4720 treatment resulting in accelerated tumor growth." (PMID 29156677, 2017). "Sorafenib is indeed not a specific inhibitor of BRAF and as such the effects may not be mediated by targeting KIAA1549-BRAF in this tumor." (PMID 24422672, 2014). "Genetic profiling of bulk tissues confirmed that all tumors contained BRAF alterations, including five tumors with the classic KIAA1549-BRAF 16:9 translocation and one tumor with a noncanonical BRAF duplication event." (PMID 31427603, 2019). "KIAA1549-BRAF fusions were found in all 9 group II tumors with BRAF duplication, but in no other group I or group II tumor." (PMID 24529209, 2014).
cancer (8 papers, 2017 to 2025). A tumor composed of atypical neoplastic, often pleomorphic cells that invade other tissues. "The most frequent fusion identified within our pediatric cancer cohort was KIAA1549-BRAF (n = 12, frequency = 5.2%)." (PMID 34863095, 2021). "There is no report that explores the role of KIAA1549 in cancers." (PMID 33639954, 2021).
CNS tumors (4 papers, 2012 to 2023). "The well-described KIAA1549::BRAF fusion was most frequently observed, being identified in 13/23 (57%) CNS tumors with a clinically significant finding." (PMID 37686670, 2023).
KIAA1549 also shares sentences with these, for which no sentence is quoted: pleomorphic xanthoastrocytoma (5 papers); diffuse astrocytoma (4); breast cancer (2); low-grade astrocytoma (2); oligodendroglioma (2); anaplastic ganglioglioma (1); brain astrocytoma (1); brainstem glioma (1); cervical cancer (1); Crohn disease (1); diffuse intrinsic pontine glioma (1); diffuse midline glioma (1); ependymoma (1); fibrosarcoma (1); high-grade glioma (1); lipoblastoma (1); lung adenocarcinoma (1); lung carcinoma (1); Lynch syndrome (1); metastatic colorectal cancer (1); neuroblastoma (1); NUT carcinomas (1); pediatric oligodendrogliomas (1); posterior fossa ependymoma (1); prostate adenocarcinoma (1); prostate carcinoma (1); Retinal dystrophy (1); spinal astrocytomas (1); subependymoma (1); thyroid papillary carcinoma (1).